FGFR2 (fibroblast growth factor receptor 2)
Diseases named in the same sentence as FGFR2 in open-access papers (continued):
Sharing a sentence is not in itself a finding about the gene and the disease.
prostate carcinoma (46 papers, 2002 to 2025). A carcinoma that arises from epithelial cells of the prostate gland. "A gene-set enrichment analysis showed that metastasis- and hypoxia-related genes are associated with a low expression of FGFR2 in prostate cancer." (PMID 30837551, 2019). "Using the TCGA database, we found that FGFR2 downregulation is associated with poor prognosis in prostate cancer." (PMID 30837551, 2019). "Accumulation of the FGFR2-IIIc splice variant of fibroblast growth factor receptor 2 (FGFR2) was associated with the progression of prostate cancer following androgen-based therapy." (PMID 31134126, 2019). "Down-regulation of FGFR-2 has been also reported in other human neoplasms, including astrocytomas, bladder and prostate carcinomas, pituitary adenomas, and FGFR-2 loss-of-function mutations have been identified in melanoma." (PMID 23977259, 2013). "Screening was based on the evaluation of chemicals’ capacity to switch FGFR2 splicing from exon 9 (with the IIIc protein isoform as a product, linked with an increased invasive phenotype in prostate cancer) to exon 8 (yielding in an IIIb FGFR2 isoform, associated with decreased malignancy)." (PMID 39861181, 2025). "The importance of FGFR2 rs2981582 gene polymorphism was studied in breast and prostate cancer." (PMID 31781300, 2019). "The restoration of FGFR2 in human prostate cancer cells enhances their sensitivity to chemotherapeutic agents." (PMID 38077251, 2023). "In some prostate cancers, the FGFR2 splice isoform, FGFR2 IIIc, has been found to be overexpressed, while FGFR2 IIIb expression is reduced." (PMID 37750089, 2023). "It contains most of the promoter region of SLC45A3 and only the non-coding region of exon 1 and results in overexpression of FGFR2 in some patients with prostate cancer." (PMID 37370984, 2023). "The screen yielded three hit compounds (a T-type Ca channel inhibitor, an L-type Ca channel inhibitor, and an opioid antagonist) that switch FGFR2 splicing and induce an epithelial phenotype in prostate cancer cells." (PMID 35402635, 2022). "Functionally, miR-628 reduces the proliferation and invasion of prostate cancer cells by repressing FGFR2 expression." (PMID 35113786, 2022). "While the initial validation was made in HEK293 cells, we have also demonstrated by RT-PCR that the LLSO compounds are changing FGFR2 splicing in PC3 prostate cancer cells." (PMID 35402635, 2022). "Until now, there are only two FGFR-targeted drugs approved for clinical use in bile duct cancer, and both of them are small-molecule inhibitors—erdafinitib (against FGFR2-3 overexpressed in prostate cancer) and pemigatinib for FGFR aberrations." (PMID 34867353, 2021). "A few fusion partners, such as SLC45A3 identified in patients with prostate cancer, can drive overexpression of FGFR2 through promoter exchange." (PMID 34732230, 2021). "In prostate cancer, the FGFR2 mRNA level was significantly lower in metastatic tumors than in either normal tissues or primary tumors." (PMID 30837551, 2019). "FGFR2 controls migration and invasion of prostate cancer cells under hypoxia by inhibiting the HIF-driven gene expression." (PMID 30837551, 2019). "It was also demonstrated that FGFR2 lowers the metastatic potential of prostate cancer cells under hypoxia by inhibiting HIF." (PMID 30837551, 2019). "We further demonstrated that FGFR2 negatively regulates cancer cell invasion under hypoxia and its expression is inversely correlated with prostate cancer progression." (PMID 30837551, 2019). "In contrast to the consistent reports of FGFR1 as an oncogene, the connection between FGFR2 and prostate cancer progression still remains controversial." (PMID 30837551, 2019).
prostate carcinoma (continued). "Loss of the intrinsic FGF7/FGF10-type 2 FGF receptor (FGFR2) pathway and gain of the ectopic type 1 FGF receptor (FGFR1) pathway are associated with the progression to malignancy in prostate cancer (PCa) and many other epithelial originating lesions." (PMID 30761180, 2019). "In bladder and prostate cancers, there is a shift in the expression from FGFR2 IIIb to FGFR2 IIIc during EMT." (PMID 29137308, 2017). "In contrast, FGFR2 has been shown to have a growth-limiting role, for example, in human prostate cancer cells and in hepatocellular cancer cells." (PMID 23185502, 2012). "FGFR1 is overexpressed in prostate cancer, and FGFR2 has been detected in both prostate cancer and benign prostatic hyperplasia." (PMID 15655558, 2005). "Of the four FGFRs, expression of FGFR1 and FGFR2 has been examined in resected prostate cancer specimens." (PMID 15655558, 2005). "Notably, the most common non–FDA-approved indications were cancers with limited targeted therapies available: pancreatic cancer for FGFR2 fusions (prevalence of 0.5%) and prostate cancer for FGFR3 and NRG1 fusions (combined prevalence of 0.4%)." (PMID 41091579, 2025). "MiR‐628 directly targets FGFR2 to inhibit the proliferation and invasion of prostate cancer cells." (PMID 37750089, 2023). "In fact, the absence of FGFR2 expression affects the mesenchymal‐epithelial signaling axis and is associated with prostate cancer development." (PMID 38077251, 2023). "Li and colleagues reported that FGFR2 and Src have oncogenic synergies, and targeting Src may serve as a therapeutic strategy for prostate cancer, in which the FGFR2-Src axis is active." (PMID 33794926, 2021). "Downregulation of FGFR2 is likely to be associated with poor prognosis in prostate cancer, but not in other types of cancers." (PMID 30837551, 2019). "Therefore, the nuclear localization of FGFR2 occurs depending on cell context and it seems to be activated especially in prostate cancer cells." (PMID 30837551, 2019). "Furthermore, FGFR2 was found to inhibit the HIF-induced migration and invasion of prostate cancer cells, providing an explanation why the mRNA levels of FGFR2 were downregulated in tumor and metastatic tissues." (PMID 30837551, 2019). "Based on the GSEA results, we hypothesized that FGFR2 plays a role in prostate cancer metastasis under hypoxic conditions." (PMID 30837551, 2019). "Thus, we tested the possibility that FGFR2 negatively regulates the hypoxia-triggered metastasis of prostate cancer." (PMID 30837551, 2019). "A class switch from FGFR2 IIIb to FGFR2 IIIc is related to the progression of prostate cancers." (PMID 22701813, 2012). "A FGFR2-IIIb to IIIc switch is related to increased invasiveness in bladder and prostate cancers." (PMID 22203889, 2012). "Similarly, the nuclear localization of FGFR2 negatively regulates HIFs in prostate cancer." (PMID 33553145, 2020). "In a repositioning screen using splicing reporters designed to follow the switch in FGFR2 splicing, we have found three novel compounds that regulate EMT and decrease tumor growth in prostate cancer mouse xenografts." (PMID 35402635, 2022). "Summarizing our results, FGFR2 interacts with HIF-1α and HIF-2α, and represses their transcriptional activities in prostate cancer cells." (PMID 30837551, 2019). "For example, HOXC6 directly regulates gene expression of Bone morphogenetic protein 7 (BMP7), Fibroblast growth factor receptor 2 (FGF2), and Platelet-derived growth factor receptor (PDGFR) in prostate cancer." (PMID 30993034, 2019). "All the selected genes show a strong relation with the disease, such as FGFR2 and BCL2, which were selected by both Net-Cox and fastcox and are involved in KEGG prostate cancer and in KEGG pathways in cancer." (PMID 27378931, 2016). "For example, HOXC6, a homeobox transcription factor, regulates the expression of genes including BMP7, FGFR2, IGFP3 and PDGFRA to influence oncogenic activities in prostate cancer." (PMID 24009521, 2013).
prostate carcinoma (continued). "In prostate cancer as well as in TGFβ-induced EMT FGFR1-IIIc is upregulated as an independent mesenchymal marker and the reciprocally downregulated IIIb receptor is FGFR2." (PMID 22203889, 2012). "Differential signaling of FGFR1 and FGFR2 has previously been investigated in mammary epithelial cells and prostate cancer cells using drug-inducible systems, in which FGFR1 and FGFR2 can be expressed and activated at the same level." (PMID 23185502, 2012). "Previous work from our group and that of others have further shown that prostate cancer cells have preferential over-expression of FGFR1 and 4 while FGFR2 and 3 are unaltered or down-regulated." (PMID 22078327, 2011). "In a subset of prostate cancers, however, these authors observed overexpression of both FGFR-1 and FGFR-2 in the epithelial cells, which correlated with poor differentiation." (PMID 12087465, 2002). "Therefore, in mouse models of prostate cancer cells, chemically induced FGFR1 dimerization/activation leads to rapid tumor growth, while inducible FGFR2 expression slows down tumor growth." (PMID 38077251, 2023). "FGFR2 mRNA levels were reduced in tumor tissues compared to normal tissues in prostate cancer and cervical cancer, but not in glioblastoma multiforme." (PMID 30837551, 2019). "Analyzing the GSEA data, we found that in prostate cancer the CHANDRAN_METASTASIS_UP gene set and a predefined HIF-1 and HIF-2 gene set PID_HIF1_AND_HIF2_PATHWAY were significantly enriched in the Low_FGFR2 group." (PMID 30837551, 2019). "Previous research identified four single nucleotide polymorphisms (SNPs) principally associated with circulating PSA levels rather than with prostate cancer risk (TERT rs2736098, FGFR2 rs10788160, TBX3 rs11067228, KLK3 rs17632542)." (PMID 26431041, 2015). "In prostate cancer, ADAM9 cleaves insulin β-chain, tumor necrosis factor (TNF)-α, transforming growth factor (TGF)-α, gelatin, β-casein, etc., and induces the shedding of epidermal growth factor (EGF), fibroblast growth factor receptor 2 (FGFR2)-IIIB and heparin-binding EGF-like growth factor." (PMID 35740916, 2022). "However, neither FGFR1 nor FGFR2 expression in prostate cancer was noted to have any significant correlation to clinical parameters including tumour grade, stage, and outcome on disease survival." (PMID 15655558, 2005). "Overall, 13.6% and 8.2% of FGFR2 fusions were in nonapproved breast and pancreatic cancer indications, respectively, 22.2% of FGFR3 fusions were in nonapproved NSCLC, and 19.4% and 10.2% of NRG1 fusions were in nonapproved breast and prostate cancers, respectively." (PMID 41091579, 2025).
Pfeiffer syndrome (42 papers, 2003 to 2025). "Here, we report the generation of three hiPSC lines derived from PBMCs of three patients, each harboring a different pathogenic variant in FGFR2 resulting in Crouzon, Apert or Crouzon/Pfeiffer syndrome." (PMID 40843495, 2025). "Pfeiffer syndrome is an autosomal dominant condition associated with mutations in both FGFR2 and FGFR1." (PMID 38353121, 2024). "For instance, Pfeiffer syndrome is caused by a gain-of-function missense mutation in FGFR1 or activating mutation in FGFR2." (PMID 35455561, 2022). "We supplemented the p.E173A mutation into a normal exome VCF file containing 33,862 variants in the FGFR2 gene associated with Pfeiffer syndrome (MIM:101600)." (PMID 28716001, 2017). "In particular, gain-of-function mutations in FGFR2 are typically associated to Apert (OMIM#101200) and Crouzon (OMIM#123500) syndromes, while both FGFR1 and FGFR2 are found mutated in Pfeiffer syndrome (OMIM#101600)." (PMID 27621700, 2016). "We report on the clinical and genetic findings in a three generation British family with Pfeiffer syndrome caused by a heterozygous missense mutation, p.Ala172Phe, located in the IgII domain of FGFR2." (PMID 23532954, 2013). "More frequently, FGFR2 is implicated and more than 40 different heterozygous mutations causing Pfeiffer syndrome have been identified in FGFR2 [Wilkie, 2008]." (PMID 23532954, 2013). "Concerning the limb anomalies, these are a more severe feature of the p.Ala172Phe mutation than most other FGFR2-associated Pfeiffer syndrome mutations." (PMID 23532954, 2013). "The majority of the patients with Pfeiffer syndrome present mutations in FGFR2, although a small number have also been identified in FGFR1 (<5%)." (PMID 20108486, 2009). "Interestingly, genotype–phenotype studies of Crouzon and Pfeiffer syndrome have shown that a closely overlapping FGFR2 mutation spectrum exists between the two, indicating that these two conditions may be on a continuum of disorders." (PMID 36755349, 2023). "Pathogenic variants in one of the most frequently affected genes, fibroblast growth factor receptor 2 (FGFR2), are associated with a multitude of phenotypically distinct syndromes, such as Crouzon, Apert and Pfeiffer syndromes, among others." (PMID 40843495, 2025). "Pfeiffer syndrome (PS) is an autosomal dominant disorder with three subtypes stemming from heterozygous mutations in the fibroblast growth factors FGFR1 and FGFR2." (PMID 36212619, 2022). "It has also been shown that the same clinical phenotype can result from mutations in different genes, such as cases of Pfeiffer syndrome with mutations in FGFR1 and FGFR2 suggesting functional redundancy among different FGFR molecules." (PMID 20108486, 2009). "These orthopedic features overlap with those seen in other syndromic craniosynostoses, particularly FGFR2‐related Pfeiffer syndrome and may reflect overlapping downstream effector pathways." (PMID 30758909, 2019).
pancreatic cancer (36 papers, 2007 to 2025). "These preclinical findings underline the critical role of FGFR1 and FGFR2 in the pathophysiology of pancreatic cancer." (PMID 39199681, 2024). "Similar correlation between low ESRP1, low IIIb, and high IIIc variant expression for FGFR2 was demonstrated by IHC in pancreatic cancer." (PMID 27650542, 2016). "In fact, overexpression of FGFR2 gene has been reported in breast, lung, stomach, and pancreatic cancers, while its down-modulation has been demonstrated in thyroid cancer and in melanoma, where FGFR2 gene can even present loss-of-function mutations." (PMID 24899248, 2014). "However, patients with FGFR2 mutations have shown an exceptionally positive response to erdafitinib in pancreatic cancer." (PMID 38607041, 2024). "However, it is unknown if FGF10/FGFR2-IIIb-signalling is associated with carcinogenesis in pancreatic cancer." (PMID 18594526, 2008). "It has also been demonstrated that FGFR2 positively regulates Akt phosphorylation in neurons and Pancreatic Cancer, and Akt phosphorylation is reduced when FGFR2 is knocked down." (PMID 33891563, 2021). "We then examined the expression of FGFR1 and FGFR2 by western blot and showed that FGFR1 and FGFR2 are widely expressed throughout these pancreatic cancer cell lines." (PMID 32457900, 2020). "FGF10 induces migration and invasion in pancreatic cancer cells through interaction with FGFR2, resulting in a poor prognosis, thus FGF10/FGFR2 signaling is a promising target for new molecular therapy against pancreatic cancer." (PMID 31607941, 2019). "Pancreatic cancer patients with high FGFR2 expression had a shorter survival time compared to those with low FGFR2 expression." (PMID 22701813, 2012). "Another ligand for FGFR2 IIIb, FGF10, induced pancreatic cancer cell migration and invasion via FGFR2 IIIb." (PMID 22701813, 2012). "This suggests that FGF10/FGFR2 signalling is a promising target for new molecular therapy against pancreatic cancer." (PMID 18594526, 2008). "Overall, the results show that FGFR2 is expressed in pancreatic cancer tissue, and that its ligand, FGF10, is expressed in stromal cells." (PMID 18594526, 2008). "Immunostaining of pancreatic cancer tissues showed that FGFR2 was expressed in cancer cells, whereas FGF10 was expressed in stromal cells surrounding the cancer cells." (PMID 18594526, 2008). "Our results show that FGF10 is expressed in stromal cells scattered around pancreatic cancer cells, suggesting a possible interaction with cancer cells expressing FGFR2-IIIb." (PMID 18594526, 2008). "Fibroblast growth factor 10 induced cell migration and invasion of CFPAC-1 and AsPC-1 pancreatic cancer cells through interaction with FGFR2-IIIb, a specific isoform of FGFR2." (PMID 18594526, 2008). "We confirmed this result by immunostaining of 76 resected pancreatic cancer tissues, and moreover, showed that the expression level of FGFR2-IIIb is correlated with prognosis and the incidence of nodal involvement." (PMID 18594526, 2008). "In this study, we investigated the molecular mechanisms underlying the aggressiveness of pancreatic cancer, and found that FGF10/FGFR2-IIIb-signalling plays an important role in inducing migration and invasion of pancreatic cancer cells." (PMID 18594526, 2008). "Pancreatic cancer tissue often contains a few islet cells (arrowheads) and we compared the expression levels of FGFR2 in cancer cells and islets." (PMID 18594526, 2008). "In conclusion, our results indicate an important role for the interaction between stromal cells and parenchymal cells mediated by FGF10/FGFR2-IIIb signalling in pancreatic cancer." (PMID 18594526, 2008). "Of note, a patient with RAS wild-type FGFR2 fused pancreatic cancer attained a deep and durable response, and it is now established that such alterations are seen in <1% patients with pancreatic ductal adenocarcinoma, indicating the need to identify these patients with clinical grade genotyping." (PMID 38602417, 2024).